TNF (tumor necrosis factor)
Diseases named in the same sentence as TNF in open-access papers (continued):
Sharing a sentence is not in itself a finding about the gene and the disease.
renal fibrosis (continued). "Tumor necrosis factor-alpha (TNF-α), predominantly found in renal tubular cells, can trigger an inflammatory response and lead to renal fibrosis 12,22,36." (PMID 39112499, 2024). "M1 macrophages can produce pro-inflammatory cytokines such as TNF-α, IL-1β, and IL-6, promoting the progression of renal fibrosis." (PMID 37861543, 2023). "The mRNA expression of proinflammatory cytokines (TNF-α and IL-1β) and renal fibrosis markers (tumor growth factor [TGF]-β1 and connective tissue growth factor) were also consistently upregulated in the renal cortex of 24-week-old db/db mice." (PMID 38016515, 2023). "Our data demonstrated that CO decreased inflammation, oxidative stress and renal fibrosis, as evidenced by quantifying the expression of TNF-α, IL-10, CAT, SOD, α-SMA and TGF-β." (PMID 37447251, 2023). "Mitochondrial dysfunction activates inflammation through the mtDNA-cGAS-STING-NF-κB pathway in renal fibrosis, with higher levels of the proinflammatory cytokines IL-6, TNF-α and IL-1β." (PMID 36959860, 2023). "Previous researches have confirmed ALPK1 promotes renal fibrosis in mice by promoting the production of pro-inflammatory cytokines IL-1β, IL-8 and TNF-α." (PMID 36732854, 2023). "In animal experiments using a murine CKD model, FGF23 regulated genes involved in inflammation and renal fibrosis (transforming growth factor-β, TNF-α)." (PMID 35872753, 2022). "The authors concluded that Klotho inhibited TGF-β and tumor necrosis factor (TNF) signaling, to decrease renal fibrosis." (PMID 35903083, 2022). "Our data demonstrated that the levels of TNF-α and IL-6 were increased in the kidney homogenate of DKD model mice, and the alteration was associated with the severity of renal fibrosis." (PMID 36448056, 2022). "TNF-α can induce the inflammation process; it is an essential pro-inflammatory mediator in the promotion of renal fibrosis." (PMID 35250597, 2022). "The results showed that AMSCs decreased Scr, M1 macrophages, M1/M2 macrophages, TNF-α, IL-6, IL-1β, and renal fibrosis and increased IL-10 and the number of M2 macrophages." (PMID 34112221, 2021). "EMT plays an important role in the pathogenesis of renal fibrosis, and TNF-α can cooperate with TGF-β to regulate EMT." (PMID 34112221, 2021). "To date, some papers have indicated that stem cells can regulate the TGF-β/Smad, NF-κB, MAPK/ERK, PI3K/AKT, and TNF-α signaling pathways to alleviate renal fibrosis." (PMID 34112221, 2021). "Several previous publications have highlighted that SKI retarded renal fibrosis by inhibiting levels of interleukin-6, interleukin-1β, and TNF-α and modulating TGF-β1/Smad3 and JAK2/STAT3 signaling pathways." (PMID 35002735, 2021). "In summary, this study demonstrated that macrophage ablation of PP2Acα ameliorates tubular cell apoptosis and renal fibrosis by reducing macrophage accumulation, macrophage activation, and TNFα production." (PMID 33934104, 2021). "We have shown that angiotensin II and TNF-α, two factors that promote macrophage infiltration and renal fibrosis in this model, can induce CypA secretion by tubular epithelial cells in culture." (PMID 32455976, 2020). "Blocking the S1P/S1PR axis by FTY720 diminished renal fibrosis, characterized by reduced expression of TNF-α, TGF-β, and the production of extracellular matrix proteins." (PMID 31379883, 2019). "These exosomes also inhibited renal fibrosis and reduced production of pro-inflammatory cytokines, i.e., tumor necrosis factor-α (TNF-α) and TGF-β1." (PMID 32082158, 2019). "In our previous study, MA-35 attenuated renal fibrosis by inhibiting both TNF-α and TGF-β1 signaling." (PMID 31484999, 2019). "SPHK2-deficient kidney-resident macrophages shifted toward the M2 phenotype due to changes in the glycolytic pathway, which reduced renal fibrosis by lowering the production of pro-inflammatory cytokines such as IL-1β and TNF-α." (PMID 31379883, 2019).
renal fibrosis (continued). "Soluble klotho also inhibited TGF-β-induced renal fibrosis and metastasis and blocked the levels of the inflammatory proteins TNFα and IFNγ." (PMID 31581134, 2019). "C/EBPβ, upregulated in injured kidneys and expressed in tubular epithelial cells, is essential for the increased Saa3 promoter activity in response to TNF-α, suggesting that C/EBPβ plays a crucial role in renal fibrosis development." (PMID 31575974, 2019). "In our study, JYYS granule significantly attenuates renal pathologic injury and renal fibrosis by downregulating the expression of IL-6, TNF-α, ICAM-1, and MCP-1, which were obviously higher in the SHR group than in WKY rats." (PMID 30598687, 2018). "Because the signaling of transforming growth factor-β1 (TGF-β1) and tumor necrosis factor-α (TNF-α) play key roles in progression of renal fibrosis, dual blockade of TGF-β1 and TNF-α is desired as its therapeutic approach." (PMID 28507324, 2017). "In the present study, we showed that the novel indole derivative compound MA-35 attenuated renal fibrosis by dual inhibition of both the TNF-α and TGF-β1 signaling pathways." (PMID 28507324, 2017). "Further, our data showed the expressions of pro-inflammatory cytokines (mcp-1, IL-1β and TNF-α) and the renal fibrosis biomarkers fibronectin (Fn) and collagen IV (Col.IV) were significantly higher in H-MCs than those in L-MCs by qRT-PCR." (PMID 28151474, 2017). "Some scholars found an infiltration of macrophages in the obstructed kidneys at 4h after UUO and these activated inflammatory cells released inflammatory mediators such as TNF-α, which, in turn, activated fibroblasts and initiated renal fibrosis." (PMID 26042668, 2015). "Additionally, the anti-inflammatory effects of these herbs become more pronounced at higher doses, as they suppress key inflammatory mediators such as TNF-α, IL-6, and NF-κB, which play a role in renal fibrosis and glomerular injury." (PMID 40151690, 2025). "Together, these immunological imbalances contribute to persistent activation of lymphocytes and macrophages, promoting the release of proinflammatory cytokines such as tumor necrosis factor-alpha (TNF-α) and interleukin-6 (IL-6), which directly contribute to glomerular injury and renal fibrosis." (PMID 41171774, 2025). "However, to our knowledge, there are currently no studies that have elucidated if TMAO in combination with the fibrotic cytokine TNF-α can enhance renal fibrosis and inflammation." (PMID 38643262, 2024). "Collecting evidence demonstrated that the infiltration of inflammatory cells, and accompanied by increased expression of monocyte chemoattractant protein-1(MCP-1), interleukin 1β (IL-1β), tumor necrosis factor α (TNF-α), and interleukin 6 (IL-6) are involved in the renal fibrosis process." (PMID 38972937, 2024). "Its expression in renal TECs promotes fibrosis not only by activating the canonical TGF-β-related fibrosis pathway, but also by activating a TNF-α related pathway, and Nrp1’s expression in myofibroblasts and pericytes also promotes the progression of renal fibrosis." (PMID 38977708, 2024). "Additionally, studies have reported that pyroptosis in renal tubules, mediated by the TNFα/Casp3/GSDME signaling pathway, leads to tubular loss and renal fibrosis." (PMID 38785272, 2024). "We identified distinct Minclehigh macrophages and neutrophils exerting pro-inflammatory and pro-fibrotic effects, which synergistically contributed to the persistence of renal inflammatory microenvironment and accelerated renal fibrosis progression by promoting TNF production." (PMID 38770013, 2024). "In addition, TNF-α-/- mice on a high-fat diet attenuate glomerulosclerosis and renal fibrosis by reducing glomerular oxidative stress." (PMID 38449859, 2024).
renal fibrosis (continued). "In vivo experiments indicated that XHYTF significantly reduced blood uric acid and creatinine levels, alleviated inflammatory cell infiltration in kidney tissues, reduced the levels of serum inflammatory factors such as TNF-α and IL1β, and ameliorated renal fibrosis in rats with UAN." (PMID 36865745, 2023). "The occurrence of renal fibrosis may be associated with the TGF-β/Smad, Notch, Hedgehog, Wnt, TNF-α, NF-κB, MAPK, JAK/STAT, PI3K/AKT, and RHO/ROCK signaling pathways." (PMID 34112221, 2021). "Mechanistically, several preliminary studies have revealed that SKI alleviated CKD and renal fibrosis by inhibiting pro-inflammatory cytokines such as interleukin-6, interleukin-1β, and tumor necrosis factor-α (TNF-α) expression and modulating TGF-β1/Smad3 and JAK2/STAT3 signaling pathways." (PMID 35002735, 2021). "TNF-α may be involved in the regulation of renal fibrosis, but the specific mechanism remains to be further studied." (PMID 34112221, 2021). "Accumulating evidence also demonstrated that the nephroprotective effects of quercetin are related to inhibiting renal tubular epithelial-mesenchymal transition and renal fibrosis and reducing the production of cytokines in DN, including IL-6, TNF-α, and IL-1β." (PMID 34349833, 2021). "Furthermore, several studies have demonstrated the inhibitory effect of emodin on renal fibrosis by suppressing the NF-ƙB p65 protein expression or the levels of ROS, TNF-α, and interleukin-6." (PMID 35002735, 2021). "In contrast, another study demonstrated that RIPK3 deficiency in the same UUO model prevents renal fibrosis without altering the mRNA expression of interleukin (IL)-1β, tumor necrosis factor (TNF)-α, and TGF-β1." (PMID 32613000, 2020). "Additionally, UTs and PIs are linked to inflammatory processes mediated by TNF-α but not by early renal fibrosis, whereas serum ACs appear to modulate immune responses, exerting pro-inflammatory and cytotoxic effects on tubular epithelial cells in early DKD." (PMID 41465208, 2025). "It was also shown that TNF-α blockade prevented the development of crescents in a rat model of crescentic glomerulonephritis and reduced renal tubular cell apoptosis, caspase activity, and several markers of renal fibrosis, in a model of unilateral ureteral obstruction." (PMID 35328704, 2022). "Moreover, PD has also been associated with removing inflammatory cytokines such as interleukin-1, -6, and TNF-α, which could induce cardiac and renal fibrosis." (PMID 35874534, 2022). "Again, the effects of macrophages on tubular cells and renal fibrosis depend on the polarization phenotype, as well as the stages after injury.Is the insertion of ‘tumor necrosis factor’ as the definition of ‘TNF’ correct?Yes, TNF stands for tumor necrosis factor." (PMID 30425237, 2018). "Beyond these indirect pathways, visceral adiposity itself promotes a proinflammatory state (marked by TNF-alpha, IL-6, MCP-1) that drives renal fibrosis and activates the renin-angiotensin-aldosterone system, leading to glomerular hyperfiltration." (PMID 40834423, 2025). "Activation of the TLR–NF-κB pathway enhances the production of pro-inflammatory cytokines, including interleukin (IL)-6, IL-1β, IL-18, and tumor necrosis factor-α (TNF-α), and stimulates transforming growth factor-β1 (TGF-β1), a key mediator of renal fibrosis." (PMID 41150807, 2025). "Animals with renal fibrosis showed decreased SOD activity and increased expression of TGF-β1, TNF, VEGF, Smad3, and Smad7, which correlated with increased expression of miR-148a-3p." (PMID 40004454, 2025). "In kidney progressive diseases, TNF-α and TGF-β1 are two pleiotropic cytokines that have been established as central mediators of inflammatory responses and renal fibrosis, respectively." (PMID 39837868, 2025). "Melatonin attenuated renal fibrosis, reduced KIM-1, TGFβ, and TNFR1 levels, improved proximal tubule and glomerular damage, and lowered adipose TNF-α levels in the obese groups." (PMID 41594577, 2025).
renal fibrosis (continued). "Improved eGFR and reduced renal fibrosis and inflammation by downregulating inflammatory genes like C3, CCL2, and TNFα and modulating angiogenesis, fibrosis, inflammation, and proliferation pathways." (PMID 38929190, 2024). "Various inflammatory factors, including TNFα, MIF, and TGF-β, have been reported to promote renal fibrosis in ADPKD, in which TGF-β has been identified as the most important regulator of renal fibrosis." (PMID 39456148, 2024). "Macrophage-related cytokines facilitate cystic renal cell proliferation or renal fibrosis in ADPKD via TGF beta, IL-17 TNF alpha, or IFNγ." (PMID 39768851, 2024). "TNF-α acts on its receptors TNF21 and TNFR1/2 and triggers the activation of various signaling pathways of renal fibrosis, including TGF-β, mitogen-activated protein kinase (MAPK), NF-κB and NADPH oxidase." (PMID 39867890, 2024). "The augmented TNF-α signaling in MCs under Rtn3-null conditions rings alarm bells for potential CKD and renal fibrosis progression." (PMID 38937317, 2024). "The reduction in macrophage numbers that has been reported with metformin in models of renal fibrosis was seen in both WT and PFKFB2 KI UUO kidneys and TNF-α as a marker of inflammation was also similarly reduced." (PMID 36757995, 2023). "Folate-deficient diets further elevated serum TC, LDL-cholesterol, IL-6, tumor necrosis factor (TNF)-α, MCP-1, TGF-β1, and leptin, but decreased IL-10 level, and thus exacerbated renal fibrosis." (PMID 37630806, 2023). "There was an age-based increase in pro-fibrotic and pro-inflammatory markers (IL-6, TNF, TGF-β1, and SNAIL1) in KO male mice that presumably contributed to renal fibrosis and renal damage (glomerular and tubular)." (PMID 37064891, 2023). "AMCZ markedly lowered the elevated levels of p-JNK, FN, Col-IV, α-SMA, IL-1β, and TNF-α in CKD rats, suggesting AMCZ attenuated renal fibrosis and inflammation through the modulation of SIRT1/JNK signaling pathway." (PMID 37089928, 2023). "The canonical stimulation for renal fibrosis has been recognized as TGF-β1, TNF-α, MCP-1, and CXCL-10." (PMID 36203223, 2022). "SQYSF significantly reduced the degree of renal fibrosis in CKD mice, and remarkably down-regulated the expressions of toll-like receptor 5 (TLR5), nuclear factor-kappaB (NF-κb), p65, tumor necrosis factor (TNF)-α, interleukin (IL)-1β and IL-6." (PMID 35184655, 2022). "The results show that SQYSF can effectively reduce renal fibrosis in CKD mice, significantly reduce the expression of inflammatory factors TNF-α, IL-1β and IL-6, and can significantly change the composition of the mouse intestinal flora." (PMID 35184655, 2022). "In conclusion, we found that UUO-induced Casp11/GSDMD-dependent NETs formation in neutrophils activated p65 translocation to the nucleus and then stimulated TNF-α and TGF-β1 production in macrophages, which promoted MMT contributing to renal fibrosis." (PMID 35941120, 2022). "Renal obstruction induced increased tissue TNF-α and several markers of renal fibrosis, whereas treatment with PEG-sTNFR1 significantly reduced each of these markers of renal fibrosis." (PMID 35328704, 2022). "The results of the Western blot analysis showed increased expressions of inflammatory-related transcription factor (p-STAT3), inflammatory cytokines (IL-1β, TNF-α), NGAL, and fibrosis-related markers (α-SMA, fibronectin) in UUO-induced renal fibrosis." (PMID 36232665, 2022). "A study reported that BMMSCs can decrease levels of tubular CCL-2, CCL-5, TNF-α, α-SMA, fibronectin (FN), and collagen IV and finally reduce tubular EMT and renal fibrosis in albumin-overloaded mice." (PMID 36268508, 2022). "VHH-0031, which can reduce the release of IL-6, TNF-α and TGF-β, is supposed to suppress renal fibrosis induced by EndMT and EMT in diabetic kidneys so as to improve renal injury and inhibit inflammatory response." (PMID 34054555, 2021).
renal fibrosis (continued). "An ELISA assay was performed to confirm the expressions of the inflammatory cytokines IL-6 and TNF-α, in UUO-induced renal fibrosis." (PMID 33806080, 2021). "Our UUO mouse model showed that a single injection of Nec-1 (inhibitor of RIPK1) ameliorated kidney injury, release of proinflammatory cytokines (IL-1β and TNF-α) and a chemokine (MCP-1), and renal fibrosis." (PMID 33390935, 2020). "Western blotting and immunohistochemical analysis showed that NF significantly induced TNF-α, CD36, SREBP-1/2, and acetyl-CoA carboxylase expression and renal fibrosis, and reduced fatty acid synthase and AMPK compared to other groups (p < 0.05)." (PMID 32575412, 2020). "Inflammatory cytokines, such as tumor necrosis factor-α (TNF-α), interleukin-1β (IL-1β), and IL-6, can directly mediate renal fibrosis through inflammatory infiltration, fibroblast activation and synthesis and degradation of ECM." (PMID 32372953, 2020). "Furthermore, over-expression of lncRNA Rpph1 related with DN-related factor galectin-3 (Gal-3) directly up-regulated inflammation factors like Mcp-1 and TNF-α and proliferation via Gal-3/Mek/Erk signaling pathway in MCs with low glucose, which may further lead to renal fibrosis." (PMID 32752143, 2020). "We found that treatment with BMSC-EVs reverse UUO-induced increase of inflammatory cytokines TNF-α, IL-6, and IL-1β and macrophage infiltration, indicating that EVs effectively protect against UUO-induced renal fibrosis by inhibiting the inflammatory response." (PMID 32586368, 2020). "Candidate genes expression involved in renal fibrosis (TGF-β1, collagen type I and III) and inflammation (TNFα, IL-1β, IL-6 and MCP-1) were also measured by real-time qPCR." (PMID 33396267, 2020). "The interaction between the JNK/MAPK and TNF/TNFR1 pathways forms the molecular basis of glomerular and renal interstitial atrophy and apoptosis, which leads to progressive renal damage and renal fibrosis." (PMID 31392215, 2019). "MSCs-derived exosomes suppressed infiltration of dendritic cells into the kidney (by regulating expression of ICAM-1) and inhibited production of the pro-inflammatory cytokines (TNF-α and TGF-β1) and renal fibrosis." (PMID 32082158, 2019). "In IgA nephropathy, melatonin can reduce the expression levels of TNF-α, MCP-1, TGF-β, collagen IV, and MMP-9 by inhibiting the transcriptional activity of NF-κB, thus delaying the progress of renal fibrosis and proteinuria." (PMID 28969091, 2017). "In conclusion, MA-35 reduces the inflammatory response by inhibiting TNF-α/IKK signaling and prevents renal fibrosis by inhibiting TGF-β1/Smad3 signaling." (PMID 28507324, 2017). "Since AAT inhibited TNF-α and TGF-β1 was activated by increased TNF-α in UUO model, we investigated the effect of AAT on TGF-β pathway in renal fibrosis." (PMID 27607429, 2016). "We demonstrated that TFNAs@PLT could reduce inflammation-mediated pyroptosis and apoptosis via Caspase-3/GSDME and NLRP3-mediated Caspase-1/IL-1β pathways in AKI, while also alleviating renal fibrosis through NLRP3/Caspase-1 and TNF-α/NF-κB pathways in CKD." (PMID 41355960, 2026). "Interestingly, Nec-1 decreased TNF-α, IL-1β, and monocyte chemotactic protein-1 expression levels as well as TGF-β and α-SMA, indicating renal fibrosis suppression." (PMID 37910384, 2023). "Also, the levels of damage markers in renal fibrosis, including ED-1 α-SMA, IL-6, IL-1β, TNF-α, TGF-β, NF-κB mRNA, CCL-2, CCL-5, collagen I, FN, collagen IV, and PCNA are decreased." (PMID 36268508, 2022). "Besides, the levels of cytokines, including the net renal release of IFN-γ, TNF-α, IL-10, and MCP-1, as well as renal fibrosis, also responded to MSC therapy." (PMID 36302933, 2022). "FMT did not prevent the expression of renal fibrosis-related genes (TGFβ1 Transforming Growth Factor beta 1) and inflammatory cytokines (IL-6, Interleukin 6 and TNFα, Tumor Necrosis Factor alpha) in the kidney." (PMID 33255454, 2020).